CD38 (CD38 molecule)
Diseases named in the same sentence as CD38 in open-access papers (continued):
Sharing a sentence is not in itself a finding about the gene and the disease.
nephrotic syndrome (3 papers, 2022 to 2025). A collection of symptoms that include severe edema, proteinuria, and hypoalbuminemia; it is indicative of renal dysfunction. "In the unique study performed in patients with multidrug dependent nephrotic syndrome reporting positive effects, obinutuzumab was associated with the anti-CD38 monoclonal antibody daratumumab proposing the unexplored frontier of combined therapies." (PMID 35222385, 2022). "Successful use of combined anti-CD20 and anti-CD38 therapy in children with complicated or resistant nephrotic syndrome has been reported." (PMID 41517310, 2025). "Only one study used obinutuzumab (single dose 1,000 mg 1.73m2) in nephrotic syndrome in combination with sequential administration of the anti-CD38 (plasma cell) monoclonal antibody daratumumab (1,000 mg 1.73m2) after 14 days." (PMID 35222385, 2022). ",13,27, 28, 29 However, and despite its primary efficacy, disease relapse, such as nephrotic syndrome and autoimmune cytopenia, has been observed and is often associated with the persistence of CD38-negative B-cells that escape drug depletion of plasma cells." (PMID 39534185, 2024).
pancreatic ductal adenocarcinoma (3 papers, 2021 to 2024). An infiltrating adenocarcinoma that arises from the epithelial cells of the pancreas. "In pancreatic ductal adenocarcinoma, CD38 was obvious increased on peripheral PD-1+CD8+T cells." (PMID 34211854, 2021).
Pancytopenia (3 papers, 2017 to 2024). An abnormal reduction in numbers of all blood cell types (red blood cells, white blood cells, and platelets). "We hypothesize that tumor microenvironment enriched in the products of CD38 ecto-enzymatic activity may keep healthy HSCs in the quiescent state leading to cancer-related pancytopenia as well as it may preserve the dormancy of cancer stem cells leading to disease persistence." (PMID 38422172, 2024).
peripheral T-cell lymphoma (3 papers, 2019 to 2025). "Variable levels of CD38 expression have been detected in approximately 80% of angioimmunoblastic T-cell lymphoma (AITL) and 60% of peripheral T-cell lymphoma, not otherwise (PTCL-NOS), thus providing a rationale for novel treatment with anti-CD38 antibodies." (PMID 36139103, 2022).
Pleural effusion (3 papers, 2020 to 2024). The presence of an excessive amount of fluid in the pleural cavity. "Cytological examination of the pleural effusion that developed 18 months later showed pleomorphic anaplastic large cells, which were negative for CD20 and positive for CD38, HHV8, and EBV." (PMID 34431125, 2021). "The FL‐SJC cells expressed CD19, CD10, CD22, HLA‐DR, CD38, Lambda and CD20, but did not express CD23, CD5 and Kappa, which was similar to that of the original FL cell from pleural effusion." (PMID 32459397, 2020).
primary systemic amyloidosis (3 papers, 2022 to 2024). Primary systemic amyloidosis (PSA) is a form of AL amyloidosis caused by the aggregation and deposition of insoluble amyloid fibrils derived from misfolded monoclonal immunoglobulin light chains usually produced by a plasma cell tumor and characterized by multiple organ involvement. "Systemic amyloidosis arises from monoclonal CD38+ plasma cells that produce misfolded immunoglobulin light chains, which form amyloid fibrils that are deposited into different tissues, leading to organ damage." (PMID 35330483, 2022).
synovitis (3 papers, 2012 to 2018). Inflammation of a synovial membrane. "This study demonstrated that marked IgG4-positive plasma cells infiltrated in rheumatoid synovium and correlated with total synovitis score, inflammatory infiltration subscore, CD3-positive T cells, CD20-positive B cells, or CD38-positive plasma cells." (PMID 25548435, 2014). "Compared with the TAbs-negative group, significantly more CD38-positive plasma cells infiltrated the TAbs-positive synovium, and a higher percentage of patients with high-grade synovitis were observed in the TAbs-positive group (5/8, 63% vs. 5/14, 36%)." (PMID 29312834, 2018). "In addition, the density of subintimal common mononuclear inflammatory cell types, including CD68+ cells, CD3+ cells, CD38+ cells, CD20+ cells, and CD79a+ cells, were significantly higher in high-grade synovitis RA patients than that in low-grade synovitis RA patients." (PMID 22656185, 2012).
acute GVHD (2 papers, 2017 to 2025). "We present in this study, a collective scientific rationale to support TNB-738, an anti-CD38 enzyme inhibitor antibody, as prophylaxis and/or treatment of inflammatory diseases, such as acute GvHD in patients undergoing allogeneic bone marrow transplantations." (PMID 41159029, 2025). "A role of CD38 positive cytotoxic cells has previously been observed in acute GVHD development." (PMID 28674539, 2017).
Acute hepatitis (2 papers, 2010 to 2022). Acute hepatic injury resulting from inflammation typically accompanied by increased serum alanine transaminase activity. "We visualized a sizeable ex vivo frequency of HCMV, Influenza and EBV-specific CD8 T cells in 13 acute hepatitis B patients and their expression of CD38/HLA-DR and Ki-67 was tested at the onset of acute hepatitis and after recovery." (PMID 20808900, 2010). "In order to elucidate, whether this activation is iNKT cell specific or a general effect on lymphocytes due to increased inflammation during acute hepatitis, we compared the expression of CD38 and CD69 on iNKT cells, as well as on CD4+ and CD8+ T cells longitudinally in each individual patient." (PMID 34905514, 2022).
acute hepatitis B (2 papers, 2010 to 2021). "For CD38-specific IgG, immunosuppressive effects are readily observed including reactivation of hepatitis B, most likely because of a severe impairment of the T cellular compartment." (PMID 33420283, 2021). "The frequency and quantity of CD8 T cells expressing CD38/HLA-DR and Ki-67/Bcl-2 phenotypic markers was analyzed in 20 patients with acute hepatitis B. Samples were collected at multiple time points from onset of disease (HBsAg+, ALT>1000 U/L) to full recovery (HBsAg- at least 1 month after onset)." (PMID 20808900, 2010).
allergic asthma (2 papers, 2018 to 2024). A asthma with a basis in a pathological type I hypersensitivity reaction. "We found increased CD19+ B cells, CD27+ memory B cells and CD27+CD38+ plasmablasts while decreased CD27− naïve B cells in children with allergic asthma." (PMID 38424520, 2024). "Our study found that CD27+CD38+ plasmablasts and CD24hiCD38hi transitional B cells increased and were correlated with serum total IgE level, CD27− naive B cells and CD24hiCD27+ B cells decreased in children with allergic asthma." (PMID 38424520, 2024). "As expected, the frequency of CD27+CD38+ plasmablasts, CD24hiCD38hi transitional B cells, CXCR5− Tph, CXCR5−ICOS+PD-1+ Tph, Tph2 subtypes and Tfh2 subtypes were weak positively correlated with serum total IgE level in children with allergic asthma." (PMID 38424520, 2024).
anorexia nervosa (2 papers, 2016 to 2021). A disorder most often seen in adolescent females characterized by a refusal to maintain a minimally normal body weight, an intense fear of gaining weight, a disturbance in body image, and, in postmenarcheal females, the development of amenorrhea. "Of those nine genes, AKAP6 and NTNG1 were genes associated with anorexia nervosa and the remaining seven (AGT, CD36, CD38, FOXP1, PPARA, PPARG and SELL) were selected for their relationship with T2D." (PMID 27483138, 2016).
aortic aneurysm (2 papers, 2021). A ruptured aneurysm located in the wall of the proximal portion of the descending aorta proceeding from the arch of the aorta. "CD38 was found to be highly expressed in aortic aneurysm tissue, and circulating CD38 was positively correlated with peak wall stress values, but the mechanisms by which CD38 was involved in AAA remain unclear." (PMID 34943043, 2021). "Moreover, CD38 was highly expressed in aortic aneurysm tissue." (PMID 33919749, 2021).
aplastic anaemia (2 papers, 2021 to 2022). "T cells from aplastic anaemia (AA) patients, especially the CD38+CD8+ T cell subset, are increased in AA patients with CD38+CD8+ T. They have higher pro-inflammatory and proliferative capacity that may contribute to the pathologic progression in AA." (PMID 36077708, 2022).
Arrhythmia (2 papers, 2017 to 2021). Any cardiac rhythm other than the normal sinus rhythm. "Our observations demonstrating that CD38−/− hearts are resistant to β-adrenoreceptor–associated arrhythmias also reveal the potential of targeting CD38-signaling pathways to treat cardiac disease." (PMID 28539361, 2017). "The percentage of CD38−/− hearts that exhibited signs of arrhythmias (in the absence and presence of 300 nm isoprenaline) during dynamic pacing and S1S2 pacing protocols was also lower than those of WT hearts." (PMID 28539361, 2017).
bladder tumor (2 papers, 2022 to 2023). "Based on the cell-surface expression patterns of three important inhibitory receptors (PD1, CD38, and Tim3), we could demarcate seven different CD8+ T cell subsets at the bladder tumor site." (PMID 37566017, 2023).
brain tumor (2 papers, 2018 to 2020). "Moreover, loss of CD38 also inhibited occurrence of spontaneous pulmonary and brain metastasis as well as progression of brain tumors induced by intracranial injected B16F10 or RMS cells." (PMID 30159123, 2018). "The underlying mechanism may involve, at least in the brain, inhibition of metastasis expansion, since loss of CD38 inhibited the outgrowth of B16F10 and RMS brain tumors that were generated by direct intracranial implantation." (PMID 30159123, 2018).
breast tumor (2 papers, 2016 to 2023). "Subsequently, we investigated the distribution of CD19+CD24+CD38+ Bregs and various subsets in the PBMCs of breast tumor patients." (PMID 27762298, 2016). "In the present study, we analyzed the expression of PD-L1 on CD19+ CD24+ CD38+ Bregs in breast tumor patients with and healthy individuals." (PMID 27762298, 2016). "Perhaps this group of CD38+ cells could be found more in ER+ breast tumors than in ER− tumors." (PMID 38133211, 2023).
Chagas disease (2 papers, 2013 to 2018). A parasitic infection caused by Trypanosoma cruzi. "CD4+CD8high T cells have been described to be a more activated population of CD4+CD8+ T cells when HLA-DR and CD38 activated markers are measured in the context of Chagas disease." (PMID 29750791, 2018).
chronic hepatitis B (2 papers, 2022). "Peripheral blood MAIT cells in patients with chronic hepatitis B express higher levels of CD38." (PMID 35585629, 2022).
chronic viral hepatitis (2 papers, 2015 to 2023). "We further showed that the choice of markers may be guided by the patient’s viral hepatitis status, and IHC scoring of CD38 can be added to the biomarker panel if the patient has viral-related HCC." (PMID 37342338, 2023). "Moreover, in accordance with our previous study, we found that high proportions of CD38+ cells, as well as CD38+CD68+ cells, were associated with improved responses to ICB, albeit only at a significant level in patients with viral hepatitis." (PMID 37342338, 2023). "Our data suggest that combining the LAG-3+ or LAG3+CD8+ cell proportions with the CD38+ or CD38CD68+ cell proportions is more useful in patients with viral hepatitis, whereas the LAG-3+ and CD8+ cell proportions may be more useful in patients without viral hepatitis." (PMID 37342338, 2023). "This suggests that CD38 alone may not be clinically useful for predicting responses in patients with no history of viral hepatitis." (PMID 37342338, 2023).
delirium (2 papers, 2023 to 2024). A disorder characterized by confusion; inattentiveness; disorientation; illusions; hallucinations; agitation; and in some instances autonomic nervous system overactivity. "However, none of the B cell subsets such as lgD+CD38+ B cells, lgD−CD38+ B cells, and CD20 on IgD− CD38+ B cells were causally associated with delirium." (PMID 38379709, 2024). "NAMPT and CD38, two enzymes catalyzing direct steps in the production and consumption of NAD+, are both elevated in CSF prior to surgery in delirium patients." (PMID 37759795, 2023).
embryonal carcinoma (2 papers, 2015). A non-seminomatous malignant germ cell tumor characterized by the presence of large germ cells with abundant cytoplasm resembling epithelial cells, geographic necrosis, high mitotic activity, and pseudoglandular and pseudopapillary structures formation. "Distinction between seminoma and embryonal carcinoma could therefore be made by the expression of SOX17/CD38 and SOX2/CD30, respectively." (PMID 25543152, 2015). "CD38 might also be useful to distinguishing between seminomas from embryonal carcinoma cells in human germ cell tumors." (PMID 26028529, 2015). "Thus, seminomas show expression of CD38 and SOX17 whereas embryonal carcinomas show expression of SOX2 and CD30." (PMID 26028529, 2015).
endometritis (2 papers, 2023 to 2024). An acute or chronic, usually bacterial infectious process affecting the endometrium. "In the clinical investigation, 27.08% of patients with IUA had endometritis, which were positive for CD38 and CD138, which was consistent with previous studies on the etiology of intrauterine adhesion." (PMID 36949381, 2023).
endotoxemia (2 papers, 2015). "Similar results were obtained in endotoxemia: the TLR4-positive CD34+ CD38− cells and the fluorescence intensity increased by 63 % and 46 %, respectively." (PMID 26272069, 2015).
fibrosis (2 papers, 2017 to 2023). the formation of excess fibrous connective tissue in an organ or tissue in a reparative or reactive process. "In contrast, the cardiac fibrosis of CD38−/− mice was significantly attenuated compared with wild‐type mice after Ang‐II infusion." (PMID 28296029, 2017).
germ cell tumor (2 papers, 2013 to 2015). A benign or malignant, gonadal or extragonadal neoplasm that originates from germ cells. "In turn, all germ cell tumors presented with a distinct CD45−, CD56+, CD10+, CD38−, CD19−, CD22−, NG2+ phenotype, except for CD10 and NG2 that were negative in 1/3 cases." (PMID 23472067, 2013). "Thus, CD38 and CD30 could potentially be used as additional markers of germ cell tumors in vivo." (PMID 25543152, 2015).
Hepatitis (2 papers, 2010 to 2023). Inflammation of the liver. "CD38/HLA-DR markers were expressed by approximately a quarter of total CD8 T cells (mean 23%, range 12–68%) at the onset of clinical hepatitis." (PMID 20808900, 2010).
IgA nephropathy (2 papers, 2024). "Felzartamab, a recombinant fully human monoclonal antibody against CD38, is currently in a phase 2a trial for patients with IgA nephropathy (IGNAZ; NCT05065970)." (PMID 37772889, 2024). "Patients with IgA nephropathy have increased the levels of CD38(+) B cells and plasma cells, which are believed to be responsible for the increased Gd-IgA1 and anti–Gd-IgA1 antibody production." (PMID 37772889, 2024). "Except for hematological tumors, CD38-targeting therapy, as one of the major discussed immune cell-depleting based strategies, has also been investigated and practiced in clinical trials of a wide range of diseases including SLE, ITP and IgA nephropathy (IgAN)." (PMID 38765013, 2024).
interstitial lung disease (2 papers, 2022 to 2024). A diverse group of lung diseases that affect the lung parenchyma. "Features of exhaustion, including loss of CD127 and CD28, and expression of TIGIT and PD-1 in CD8 T cells are strongly associated with interstitial lung disease and autoimmune cytopenias, whereas CD8 T cell activation with elevated HLA-DR and CD38 expression predict non-infectious diarrhea." (PMID 35589883, 2022).
juvenile idiopathic arthritis (2 papers, 2016 to 2022). Juvenile idiopathic arthritis (JIA) is the term used to describe a group of inflammatory articular disorders of unknown cause that begin before the age of 16 and last over 6 weeks. "CD56brightCD16− NK cells from blood of juvenile idiopathic arthritis patients highly expressed CD38 molecules, and CD56brightCD16− NK cells inhibited autologous CD4+ T cell proliferation via the CD38-mediated pathway." (PMID 36268017, 2022).
kidney damage (2 papers, 2008 to 2019). "Our results showed more aggravated kidney damage in CD38−/− mice than in WT mice, accompanied with an increase of proinflammatory cytokine expression." (PMID 30915370, 2019).
lung diseases (2 papers, 2018 to 2021). "Using the expressions of PD‐1, chemokine C–C motif receptor 7 (CCR7), CD45RA, CD38 and HLA‐DR, we analyzed proportion of exhausted and activated CD4+ and CD8+ T cells in healthy volunteers and patients with lung diseases, respectively." (PMID 34841705, 2021).
lymphoplasmacytic lymphoma (2 papers, 2006 to 2013). A clonal neoplasm of small B-lymphocytes, lymphoplasmacytoid cells, and plasma cells involving the bone marrow, lymph nodes, and the spleen. "The immunohistochemistry revealed positive staining for CD20, CD79a, and Lambda of B cell markers and negative for CD38 and CD138 of plasma cells, and so this patient was diagnosed with lymphoplasmacytic lymphoma." (PMID 24385833, 2013).
macrophage activation syndrome (2 papers, 2025 to 2026). A complication of rheumatic disease that is caused by excessive activation and uncontrolled proliferation of T lymphocytes and well-differentiated macrophages. "In patients with secondary Hemophagocytic LymphoHistiocytosis (sHLH), including Macrophage Activation Syndrome (MAS), flow cytometry can reveal an increased frequency of CD4dimCD8+ T cells, expressing high levels of activation markers CD38 and HLA-DR." (PMID 40627382, 2025).
metastatic prostate carcinoma (2 papers, 2018 to 2021). A carcinoma that arises from the prostate gland and has spread to other anatomic sites. "In this study, we identify CpG methylation in the CD38 locus in primary and metastatic prostate cancer." (PMID 30258629, 2018). "We identified methylation of the CD38 promoter in primary and metastatic prostate cancer." (PMID 30258629, 2018).
muscular dystrophy (2 papers, 2023 to 2024). Muscular dystrophy (MD) refers to a group of more than 30 genetic diseases characterized by progressive weakness and degeneration of the skeletal muscles that control movement. "A connection between CD38 and senescence was also demonstrated in a disease model of muscular dystrophy (mdx mice)." (PMID 37424179, 2024).
myeloproliferative neoplasm (2 papers, 2020 to 2025). A clonal hematopoietic stem cell disorder, characterized by proliferation in the bone marrow of one or more of the myeloid (i.e., granulocytic, erythroid, megakaryocytic, and mast cell) lineages. "In this work, we aimed at optimizing a workflow for cell immunostaining, fixation and WGA dedicated to the single-cell genomic analysis of the hematopoietic CD34+CD38- stem compartment, in which originate hematological malignancies such as Myeloproliferative Neoplasms." (PMID 33036143, 2020).
nasal polyp (2 papers, 2021 to 2024). "Recently, CD38 was demonstrated to be differentially expressed in human nasal polyp mast cells where CD38low were of the MCTC subtype, while CD38high MCs were a heterogenous pool of both MCT and MCTC cells." (PMID 35058936, 2021).
neuropathy (2 papers, 2022 to 2024). A disorder affecting the nervous system that manifests with pain, tingling, numbness, and/or muscle weakness. "In contrast, knockout of PARP1, CD38, SARM1, and DBC1 protects mice against neuropathy induced via a high fat diet (HFD) or chemotherapy-induced neuropathy." (PMID 38256175, 2024). "In contrast, the knockout of PARP1, CD38, SARM1, and DBC1 protect mice against HFD-induced neuropathy or chemotherapy-induced neuropathy." (PMID 35563288, 2022). "The activation of PARP1 or CD 38 also promotes axonal degeneration, whereas the knockout of PARP1, CD38, SARM1, and DBC1 protect mice against high fat diet (HFD)-induced neuropathy or chemotherapy-induced neuropathy." (PMID 35563288, 2022).